ANPEP (alanyl aminopeptidase, membrane)
Diseases named in the same sentence as ANPEP in open-access papers (continued):
Sharing a sentence is not in itself a finding about the gene and the disease.
tumor (continued). "Interestingly, the spatial clusters C3 and C5 both expressed high levels of stem cell markers OLFM4, SOX9, and ANPEP, corresponding to the metaplasia and tumor regions, respectively." (PMID 39950944, 2025). "Moreover, the down‐regulation of ANPEP was not only significant in the discovery cohort, TCGA cohort, and validation cohort but also in comparisons between the normal and tumor tissues." (PMID 36748835, 2023). "Clinical verification of three tumor-associated proteins with elevated levels in comparison to all the three control types—5′-nucleotidase isoform 2 (NT5E), aminopeptidase N (ANPEP) and neprilysin (MME) was carried out using individual plasma samples from early or advanced stage GBC." (PMID 34876625, 2021). "Recently, studies about 270 NSCLC patients reported that ANPEP expression in endothelial cells, vessel-associated stroma cells and tumor cells had no prognostic effect in entire NSCLC." (PMID 34633989, 2021). "However, TMPRSS2 exhibited very low expression levels, and also negatively correlated with tumor stages in KIRP tumor tissues along with ANPEP (ρ = −0.153, p < 0.05)." (PMID 33330620, 2020). "ANPEP was thought as an important therapeutic target for cancers and inhibition of it could suppress tumor cells proliferation and migration." (PMID 32127786, 2020). "Accordingly, it suggested that these 3 downregulated proteins (ANPEP, CAV1, and TGM2) were potentially remained downregulated and might associate with the loss of vascular structures in tumor metastases." (PMID 32756007, 2020). "Next, we examined the effect of suppression in ANPEP expression at xenograft tumor growth." (PMID 32756007, 2020). "For instance, ANPEP was reportedly involved in cell migration and tumor metastasis." (PMID 31097021, 2019). "Within tumor tissue in the adequate iron group, and more so in tumors from the excess iron diet group, we found there was also significantly greater (p ≤ 0.05) expression of proteins involved in protein degradation (ANPEP, DPP7, ITGB1, PSMA1, PSMA2, PSMA3, and SERPINB1)." (PMID 38732562, 2024). "We thus speculated that ANPEP may play a tumor‐suppressive role in EOCRC." (PMID 36748835, 2023). "Three proteins, NT5E, ANPEP and MME, were selected for clinical verification based on differential abundance in GBC compared to all control types (healthy, GSD and XGC cases), their association with tumor state in other cancers and functional relevance to tumor condition." (PMID 34876625, 2021). "However, ANPEP overexpression reduced suspended cell-inoculated tumor growth." (PMID 32756007, 2020). "However, we also found that aminopeptidase N (ANPEP)/CD13 was inhibited in two tumor types." (PMID 32127786, 2020). "We also assessed the protein expression of ANPEP, APOB, and GLP1R in tissues from the primary, tumor, and metastatic groups using IHC staining." (PMID 40696350, 2025). "We found that CSCs expressed high levels of tumor stemness genes (PROM1, CD24, CD47, ANPEP, ALDH1A1, OLFM4, and SOX9), and demonstrated a high cancer stemness score, along with activation of the cancer driver genes EGFR and ERBB2." (PMID 39950944, 2025). "The tripeptide NGR (Asn‐Gly‐Arg) was notably competent for anchoring tumor‐related angiogenic vessels, molecularly targeting aminopeptidase N (ANPEP/CD13) in endothelial cells." (PMID 37547175, 2023). "In the tumor sample inoculated with shLuc-transfected cells, several vascular cavities were seen with positive CD31, ANPEP, SDC1, and integrin β4 immunostainings." (PMID 32756007, 2020). "In order to reconfirm this result, we overexpress ANPEP protein and examined its effects in protein expressions of ANPEP/SDC1/integrin β4 axis and xenograft tumor growth." (PMID 32756007, 2020). "CD13 (metalloprotease; aminopeptidase N; ANPEP/APN) is also an important regulator of angiogenesis and is overexpressed in tumor cells." (PMID 27786256, 2016).
tumor (continued). "With regard to our finding that ANPEP expression was reduced in EOCRC, we found that the hypermethylation of cg26222247 was also significantly higher in the EOCRC than in the LOCRC samples for both the normal and tumor tissues in our discovery cohort." (PMID 36748835, 2023). "The gene ANPEP/LOC112653425, involved in glutathione metabolism, the renin–angiotensin system, and hematopoietic cell lineage, was found to be one of the most prevalent DEGs in IBD enteroids and tumor enteroids." (PMID 35884586, 2022). "Tumour epithelial cells were further reclustered into two distinct subclusters (Subcluster 1 and Subcluster 2), and DUSP9 was predominantly expressed in Subcluster 1, which was enriched with other oncofetal and stemness‐related genes such as AFP, GPC3, IGF2, ANPEP and EPCAM." (PMID 41383134, 2025). "Specifically, the NR3C2, ANPEP, and FCGRT genes were significantly upregulated in tumor tissues, while PIK3R1, MME, SCD, and SERPINE1 genes were notably downregulated." (PMID 41011246, 2025). "By contrast, ANPEP expression was not just consistently and significantly lower in EOCRC samples compared with LOCRC samples, including Western blot analysis, but also in comparisons between the tumor and normal tissues." (PMID 36748835, 2023).
cancer (195 papers, 2004 to 2026). A tumor composed of atypical neoplastic, often pleomorphic cells that invade other tissues. "As an example, aminopeptidase N (ANPEP) has been associated with the growth of different human cancers and has been suggested as a suitable target for antineoplastic treatment approaches." (PMID 30813269, 2019). "Studies of mRNA and protein expression of ANPEP in malignancy are conflicting, with some suggesting an overexpression as an indicator of cancer presence and a role for ANPEP in invasion and metastasis whereas others propose that reduced expression is associated with cancer." (PMID 22075945, 2012). "Genes encoding ANPEP, PROK2, CHP2, PTPRM, AREG, and COL7A1 showed significant differential expression in SRC and PC carcinomas." (PMID 35626106, 2022). "We showed that the genes encoding ANPEP, PROK2, CHP2, PTPRM, AREG, and COL7A1 were differentially expressed between SRC and PC carcinomas." (PMID 35626106, 2022). "Among the genes encoding zinc ion-binding proteins, three (ANPEP, LIMCH1 and NR2F2) are known to be cancer-related." (PMID 21209903, 2010). "Interestingly, many cancer cells overexpress this protease, and in fact ANPEP has been the subject of research as a potential anti-cancer therapeutic drug." (PMID 36680018, 2023). "In addition, the downregulated expression of ANPEP has also been observed in different types of carcinomas." (PMID 37371512, 2023). "There are some papers that have studied ANPEP expression in PCa cell lines and suggest that ANPEP shows reduced expression in cancer cells and that there is a significant reduction in expression between LNCaP and PC3 (which have a more aggressive phenotype) cells." (PMID 22075945, 2012). "Notably, the APOE transcript was upregulated in 6 cancers, while the expression of ANPEP was downregulated in seven cancers, and it may have oncogenic and antitumor effects." (PMID 35141230, 2021). "Methylation of ITGAL and ANPEP were down-regulated, while methylation of CD69 and PTPRC were up-regulated in cancer." (PMID 34633989, 2021). "Genes that are associated with increased proliferation and invasion in several cancer types, such as DPT, ANPEP, and LRRN1, were among the most concordant DEG in this signature." (PMID 34311724, 2021). "DPP4, ANPEP, and ENPEP RNA expression were also elevated in renal tumors compared to other cancer tissues." (PMID 33330620, 2020). "In this study, we did landscape profiling of CoV receptors (viz ACE2, TMPRSS2, ANPEP, ENPEP, and DPP4) in various normal and cancer cells." (PMID 33330620, 2020). "In contrast to ANPEP, AZGP1, the six metallothioneins and the network HUB genes, only one of the zinc-transporters (SLC39A1 - upregulated) showed any consistent differential expression between high- and low-grade cancer samples." (PMID 35707723, 2022). "The signature highlights genes AZGP1, ANPEP and metallothioneins with zinc-binding properties not previously studied in the prostate, and the expression of these genes are reduced in more aggressive cancer lesions." (PMID 35707723, 2022).
infection (87 papers, 2010 to 2026). The state of being infected such as from the introduction of a foreign agent such as serum, vaccine, antigenic substance or organism. "Infection of all nine cell lines with HCoV-229E revealed that, again, TMEM41B knockout significantly reduced viral RNA by 24 hours post-infection (by ~3 orders of magnitude) in a similar manner to loss of the viral receptor ANPEP." (PMID 34043740, 2021). "The biological relevance of ANPEP as PEDV receptor is supported by the ability of transgenic mice expressing porcine ANPEP becoming susceptible to infection with the virus." (PMID 30315482, 2019). "The purpose of this study was to determine the biological relevance of ANPEP as a virus receptor for PEDV and TGEV by investigating the infection of pigs possessing CRISPR/Cas9-mediated edits in ANPEP." (PMID 30315482, 2019). "Additionally, IPA identified the top significantly affected molecules and G9P infection had a staggering >200 fold-change increase of ANPEP and TMIGD1, suggestive of an increased granulocyte and cell recovery response." (PMID 37515094, 2023). "In addition to ACE2, ANPEP has also been shown to act as a co-receptor in the first phase and has been suggested to be very important for the virus to develop the infection." (PMID 38813031, 2023). "rVSV-ΔG-EGFP-S infection was significantly reduced in ANPEP KO cells." (PMID 37630636, 2023). "ANPEP null pigs did not support infection with TGEV, but retained susceptibility to infection with PEDV." (PMID 30315482, 2019). "We used an sgRNA lentivirus targeting the randomly selected ANPEP gene to assess the capacity of this cell line for gene editing, and found that gene-editing activity tended to be stable ~6–10 days post-infection of the sgRNA-harboring lentivirus in PK-15-Cas9 cells." (PMID 33057066, 2020). "In this study, we investigated the variability in several pig genes (ACE2, ANPEP, DPP4 and TMPRSS2) that can serve as receptors or protease for priming the infection of coronaviruses." (PMID 33564056, 2021). "During the initiation and propagation stages of infection, several renin-angiotensin system (RAS) family genes (e.g., ACE2 and ANPEP) are upregulated, whereas others (e.g., epidermal growth factor receptor - EGFR and insulin-like growth factor 2 receptor - IGF2R) are downregulated." (PMID 38813031, 2023). "Data indicated that CRNG significantly increase KITLG, FOXP3 and miR-451, and decrease ANPEP and STAT5A mRNA expression, suggesting that CRNG may be necessary for the modulation of antiviral immunity, inflammation and pathogen infection." (PMID 31178726, 2019). "Here we confirm that ANPEP is required for the infection of pigs with TGEV, but is not a biologically relevant receptor for PEDV." (PMID 30315482, 2019). "Moreover, microarray assay in combination with CRNG interference and overexpression showed that the differential genes such as ANPEP, KITLG, STAT5A, FOXP3, miR-451, IL-2, IL-10, IL-6, and TNF-α are mainly involved in viral and pathogens infection and the immune-inflammatory responses in PK-15 cells." (PMID 31178726, 2019). "When taken together, these results showed that while ANPEP may play a supporting role for infection the absence of ANPEP did not significantly affect infection of pigs with PEDV." (PMID 30315482, 2019). "Similarly, ANPEP expression in monocytes and macrophages may provide an alternative non-epithelial route of infection for other coronaviruses such as CoV-229E." (PMID 32463365, 2020).
neurodegenerative disease (1 paper, 2022). A disorder of the central nervous system characterized by gradual and progressive loss of neural tissue and neurologic function. "In fact, increased ANPEP expression is a hallmark of inflammation in neurodegenerative disease, and impaired ANPEP activity has been investigated as a target for anti-inflammatory therapy." (PMID 35464443, 2022).
ANPEP also shares sentences with these, for which no sentence is quoted: hepatocellular carcinoma (29 papers); acute myeloid leukemia (24); lung carcinoma (22); fibrosarcoma (15); glioma (12); Obesity (12); Stroke (12); pancreatic cancer (11); Sepsis (11); acute leukemia (10); thyroid cancer (10); colorectal cancer (9); myeloid leukemia (8); colon adenocarcinoma (7); lymphoma (7); acute promyelocytic leukemia (6); myeloid neoplasm (6); cervical carcinoma (5); Hyperglycemia (5); Insulin resistance (5); ischemic stroke (5); metabolic syndrome (5); myocardial infarction (5); Alzheimer disease (4); Anxiety (4); autoimmune disease (4); Cognitive impairment (4); metastatic tumor (4); monocytic leukemia (4); psoriasis (4).
A further 200 diseases each share a sentence with ANPEP in 4 papers or fewer.